EGFR (epidermal growth factor receptor)
Diseases named in the same sentence as EGFR in open-access papers (continued):
Sharing a sentence is not in itself a finding about the gene and the disease.
glioblastoma (continued). "This inconsistency has to be investigated in more detail, since LuzP6 is coded for on chromosome 7, which can show gains in glioblastoma and carries coding regions for EGFR and PDGFA." (PMID 31006040, 2019). "GSC neurospheres established from longitudinal patient glioblastoma samples before and after targeted treatment with the EGFR inhibitor dacomitinib recapitulated the molecular changes observed in the patient tumours." (PMID 30644426, 2019). "This is an antiproliferative miRNA that interferes with biological pathways that target genes involved in glioblastoma pathogenesis, including EGFR and platelet-derived growth factor receptor alpha (PDGFRA), E2F3a, and WEE1." (PMID 31013819, 2019). "The methylation class of the tumor was an IDH wildtype glioblastoma with a 0.99 calibrated score and the CNV plot showed EGFR amplification and PTEN loss." (PMID 31806041, 2019). "In glioblastoma, clinical trials on EGFR-TKIs, such as gefitinib, erlotinib, and dacomitinib, demonstrated that their clinical benefits were limited or absent." (PMID 31614999, 2019). "Glioblastoma multiforme expresses a characteristic epidermal growth factor receptor (EGFR) mutant (EGFRvIII, de 2–7) that signals constitutively, and is more tumourigenic than the wild-type receptor." (PMID 31382374, 2019). "miR-299-5p is generally upregulated in glioblastoma, and its depletion can reduce the activity of the EGFR-related signaling pathway (MAPK/ERK)." (PMID 31013819, 2019). "As previously reported, glioblastoma tumor-initiating cells have varying degrees of responsiveness to EGFR-TKIs." (PMID 31284441, 2019). "Vengoji and colleagues recently reported that BBR has anti-tumor effects through inhibition of the mTOR-signaling pathway and can induce senescence of human glioblastoma cells by downregulating the EGFR–MEK–ERK signaling pathway." (PMID 31841506, 2019). "A similar approach using EGFR-specific affibody-phthalocyanine conjugates for PIT in a glioblastoma animal model has been reported." (PMID 30669481, 2019). "In about 30% of glioblastomas, the 2–7 exons of EGFR are deleted which gives rise to an extracellular domain truncated EGFR named EGFRvIII whose tyrosine kinase is constantly active due to its ligand independent dimerization." (PMID 31508364, 2019). "Growing evidence suggests that HDAC inhibitors remarkably decrease the transcription of genes, particularly those that have high copy numbers, such as EGFR, in different types of cancers, including glioblastoma, breast cancer, and so on." (PMID 31013819, 2019). "It has been shown that 40–50% of glioblastoma patients have dysregulated EGFR, and approximately half of these co-express the mutant receptor EGFR variant III (EGFRvIII)." (PMID 31013819, 2019). "Screening with an shRNA library using glioblastoma cells revealed that the combined inhibition of dopamine D2 receptors and EGFR-TKI leads to synergistic tumoricidal activity through suppression of the MAP kinase pathway." (PMID 31284441, 2019). "D2C7-IT is a novel immunotoxin (IT) targeting wild-type epidermal growth factor receptor (EGFRwt) and mutant EGFR variant III (EGFRvIII) proteins in glioblastoma." (PMID 31142380, 2019). "Downregulation of NHE9 expression by miR-135a acidifies sorting endosomes, limiting EGFR traffic to the glioblastoma cell membrane." (PMID 31013819, 2019). "They analyzed that approximately 40% of primary glioblastomas show alteration of the EGFR gene, while this pattern has rarely been identified in secondary glioblastomas." (PMID 31013819, 2019). "Glioblastoma cells with EGFR gene amplification often co-express a constitutively active EGFR mutant form (EGFRvIII), which drives tumorigenicity and mediates radio- and chemoresistance." (PMID 31798595, 2019).
glioblastoma (continued). "The combination of HDAC inhibitor + EGFR inhibitor can prevent the development of resistance in glioblastoma cells." (PMID 31013819, 2019). "As the EGFR gene is amplified in 40% of primary glioblastomas, therapy targeting EGFR was considered promising." (PMID 31284441, 2019). "First, we reanalyzed data from our laboratory to compare wild‐type U87 glioblastoma cells with isogenic U87‐EGFRvIII cells overexpressing a constitutively active EGFR mutant." (PMID 30979792, 2019). "This miRNA can positively regulate the EGFR signaling pathway, and its inhibition sensitizes glioblastoma cells to anti-EGFR therapy." (PMID 31013819, 2019). "The epidermal growth factor receptor (EGFR) is frequently overexpressed in approximately 40% of glioblastoma (GBM)." (PMID 30824700, 2019). "miR-7 is a common regulator of the PI3K/Akt and Raf/MEK/ERK pathways, both of which are launched by EGFR, and is a potential glioblastoma suppressor that acts by targeting multiple oncogenes related to the downstream pathway of EGFR." (PMID 31013819, 2019). "For instance, the recombinant IT D2C7-(scdsFv)-PE38KDEL, specific for both wild-type epidermal growth factor receptor (EGFR) and for its deletion mutant EGFRvIII exhibited potent antineoplastic effects against intracranial glioblastoma xenografts." (PMID 31108917, 2019). "In the same way a TF upregulation was found in squamous cell carcinoma (SCC) and glioblastoma multiforme (GBM), especially when mutations of the epidermal growth factor receptor (EGFR) and loss of E-cadherin occur." (PMID 30949114, 2019). "The contribution of abnormal EGFR signaling to glioblastoma has led to the development of various therapies targeting the EGFR signaling pathway." (PMID 31013819, 2019). "Treatment with epigenetic regulators or in combination with EGFR inhibitors represents a new hope for treatment of glioblastoma." (PMID 31013819, 2019). "Glioblastomas (GBs) frequently display activation of the epidermal growth factor receptor (EGFR) and mammalian target of rapamycin (mTOR)." (PMID 31510109, 2019). "EGFR is particularly overexpressed in over 90% of glioblastomas and constitutes an interesting target for glioblastoma RIT." (PMID 31354487, 2019). "For instance, glioblastoma multifome (GBM) cells expressing epithelial growth factor receptor variant III (EGFRvIII), a constitutive active mutant form of EGFR, incorporate this receptor into EV." (PMID 30699970, 2019). "CD73 is also highly expressed on glioblastoma cells, positively correlated with EGFR expression, and its upregulation has been shown to both raise adenosine concentrations and lower the number of T cells in the glioblastoma microenvironment." (PMID 31142380, 2019). "Despite great advancements over the past decade in targeting EGFR in glioblastoma using synthetic products, there is still considerable room for further progress." (PMID 31013819, 2019). "Overexpression of EGFR and EGFRvIII is frequently observed in glioblastoma, and is a key contributing factor in the progression of this disease." (PMID 31013819, 2019). "Future studies will be necessary to examine the EGFR/MAP4K4/Arp2 pathway in glioblastoma invasion further." (PMID 31570734, 2019). "We found EGFR amplification to be targeted in 89% of glioblastomas and one astrocytoma grade II, with a total of 90% of cases with amplified EGFR genes." (PMID 30871102, 2019). "CAR T cells targeting EGFRvIII, a truncation mutant of EGFR that is common in glioblastoma, were safe but unable to eradicate the tumor, likely due to nonuniform expression of the target protein and antigen escape." (PMID 31903167, 2019). "Primary kinase-activating mutations in EGFR occur often in NSCLC and glioblastoma, but rarely in other types of cancers." (PMID 31508364, 2019).
glioblastoma (continued). "Multiple genes implicated in cell proliferation and differentiation, including the telomerase reverse transcriptase gene, c-MET, EGFR and NF1, have been showed to be mutated or overly expressed in glioblastoma." (PMID 30787206, 2019). "The EGFR gene amplification was claimed in 40–60% of primary glioblastomas, rarely in the secondary ones." (PMID 31801254, 2019). "High-level EGFR amplification was previously detected in the invasive subpopulation within heterogeneously amplified glioblastomas." (PMID 31036078, 2019). "MVP has been reported to activate the EGFR/PI3K/AKT signaling pathway in glioblastoma and colon cancer cells." (PMID 31092229, 2019). "We then used western blot and cell surface quantification of EGFR in three established glioblastoma cell lines (T98, U251T, and U87) to assess their ability to recapitulate tumor EGFR expression." (PMID 31903167, 2019). "Expression of wild-type EGFR was found among all gliomas, but was more prominent in glioblastomas than in grade II/III gliomas (mean FPM = 612 vs. 126; p = 0.0061)." (PMID 31747973, 2019). "One of the first glioblastoma RIT clinical trials using a mAb directed against the EGFR antigen and radiolabeled with iodine-125 showed a significant and promising increase in median survival." (PMID 31354487, 2019). "miR-7 transfection in glioblastoma cells leads to repressed invasiveness, enhanced apoptosis, and negatively regulated EGFR and Akt pathways, fulfilling the basic requirements of a tumor suppressor." (PMID 31013819, 2019). "CMTM1 overexpression in the glioblastoma cell line A172 also promotes the proliferation and migration of tumor cells, which is likely to be achieved by the activation of epidermal growth factor receptor (EGFR), Src family kinase, and Wnt signaling." (PMID 31754330, 2019). "As an activator of cell proliferation, EGFRvIII isexpressed only by a specific fraction of glioblastoma cells, thus inducingproliferation not only of these cells, but also of the adjacent cellsexpressing wild-type EGFR." (PMID 31413876, 2019). "Some miRNA expression is decreased during the progression of glioblastoma, which targets EGFR transcripts to decrease the total number of receptors made by targeting NHE9." (PMID 31013819, 2019). "In fact, results from the INTELLANCE 2 trial with the late-stage candidate depatuxizumab mafodotin (ABT-414; Deputax-M) in combination with temozolomide showed OS improvement in epidermal growth factor receptor (EGFR)-amplified recurrent glioblastoma." (PMID 31159480, 2019). "We previously showed that berberine-induced senescence of U87 glioblastoma cells is mediated by the downregulation of EGFR and RNAi of EGFR alone can induce senescence." (PMID 30910997, 2019). "Another study investigated the effects of RNAi-mediated gene silencing of both rictor and EGFR in glioblastoma cells." (PMID 31817676, 2019). "In accordance with our findings, epidermal growth factor receptor (EGFR) is overexpressed in nearly 60% of primary glioblastoma cases." (PMID 31261921, 2019). "The therapeutic utility of CAR-engineered NK cells for the treatment of glioblastoma has so far mainly been investigated in preclinical studies with effector cells targeting EGFRvIII, EGFR or ErbB2." (PMID 31798595, 2019). "Receptor tyrosine-protein kinase ErbB-3 (ERBB3) is known to mediate glioblastoma cancer stem-like cell resistance to EGFR inhibition." (PMID 30626092, 2019).
glioblastoma (continued). "Nearly 77% (36 of 47) of the glioblastoma samples within the classical subtype exhibited EGFR gene amplification." (PMID 30957015, 2019). "Another study, which was performed on subgroupings (primary and secondary glioblastomas) described five cases out of 34 glioblastomas with EGFR amplification." (PMID 31013819, 2019). "The feasibility of RIT and PRRT in glioblastoma therapy is well established, and the first clinical trial results appear to be promising with well-known targets (e.g., tenascin, EGFR, or neurokinin receptors)." (PMID 31354487, 2019). "The promising pre-clinical safety, pharmacokinetic, and antitumor results from the canine EGFR targeted, doxorubicin minicells study subsequently informed the design of a Phase I clinical trial applying this approach in human recurrent glioblastoma patients." (PMID 31788444, 2019). "For example, in glioblastoma stem cells, Bevacizumab, a blocker of EGFR, or Temozolomide, in combination with chloroquine (a late-stage autophagy inhibitor), enhance drug toxicity, thus affecting glioblastoma CSCs survival." (PMID 30728463, 2019). "Similar results with higher variances (possibly due to the smaller size of the datasets) can be observed for EGFR amplifications in glioblastoma and LUSC, for PVT1 amplifications in ovarian cancer and for PTEN deletions in sarcoma." (PMID 31379928, 2019). "The amplification of EGFR was identified in approximately 40–50% of all cases of glioblastoma (GBM), 2007 WHO grade IV, the most malignant of diffuse gliomas." (PMID 31623593, 2019). "Upon staining of γH2AX reflecting DNA double-strand breaks, nuclei of LN18 glioblastoma cells showed strong signal enhancements 1 h after treatment with 213Bi-anti-EGFR-MAb compared with untreated controls." (PMID 31165773, 2019). "Genes known to be the most frequently amplified in glioblastoma, EGFR, CDK4, PDGFRA, MDM2, MDM4 are all found to be involved in tumorigenesis of a variety of cancers and are members of several signaling pathways notoriously involved in cancer." (PMID 30871102, 2019). "Conversely, Whites are diagnosed with more primary glioblastomas, which have been found to have more EGFR amplification." (PMID 29927955, 2018). "The siRNA applied to glioblastoma cells in vitro was shown to reduce gene expression of EGFR and β-catenin and significantly inhibit their migratory as well as invasive ability." (PMID 30374421, 2018). "Thus, a vaccine called Rindopepimut, targeting the EGFR deletion mutation EGFRvIII, consisting of an EGFRvIII-specific peptide conjugated to keyhole limpet hemocyanin, was developed and tested in clinical trials for the treatment of EGFRvIII-positive glioblastomas." (PMID 30279357, 2018). "Recent studies have demonstrated that EGFR activation drives TF upregulation in tumor cells derived from glioblastoma and vulvar cancer." (PMID 30093972, 2018). "WTAP enhances cell proliferation, migration, invasion and tumorigenicity of glioblastoma cells in xenograft via mediating phosphorylation of epidermal growth factor receptor (EGFR) and AKT." (PMID 30062093, 2018). "On the other hand, GRB2 is a key protein in epidermal growth factor receptor signaling in the Glioblastoma tumoroginesis pathway." (PMID 30059495, 2018). "The SEPT14 gene was also found fused to the EGFR gene in 4% of glioblastoma sensitive to EGFR inhibitors." (PMID 29844869, 2018).
glioblastoma (continued). "This analysis allowed the identification of some new gene rearrangements frequently observed in glioblastomas: in fact, in 24% of glioblastomas rearrangements between EGFR and adjacent genes were observed; these rearrangements tended to be part of focal gain." (PMID 30279357, 2018). "We have previously shown that inhibition of EGFR or mTORC1 signal transduction can protect human glioblastoma cells from hypoxia-induced cell death." (PMID 30129426, 2018). "Although we did not quantitatively assess changes in proliferation rate or cell death, other studies targeting EGFR within in vivo glioblastoma models resulted in minimal effects on proliferation, and a predominant effect on tumor invasion." (PMID 30573757, 2018). "Especially, EGFR and PTEN in the dysregulated pathway identified in our study are reported to be associated with glioblastoma in more than 100 previous studies." (PMID 29337288, 2018). "Overexpression of EGFR has been observed in many primary tumor types including lung, pancreas, breast, and glioblastoma while overexpression of HER2 has primarily been observed in breast and ovarian cancers." (PMID 29342193, 2018). "EGFR-target TAAs in glioblastoma (GBM), HER2-target TAAs in GBM and sarcoma, and MSLN-target TAAs in mesothelioma have all demonstrated an effective on-target therapeutic response with increased overall survival leading to the development of clinical trials." (PMID 29546043, 2018). "The molecular alterations in IDH-wildtype glioblastomas include mutations in the TERT promoter, chromosome 10q loss, 7p gain or EGFR amplification, (some with an additional EGFR vIII mutation), ID2, MYCN and PDGFRA amplifications and CDKN2A/B deletions." (PMID 29098416, 2018). "In mouse models of glioblastoma development it was provided evidence that concomitant activation of EGFR and ablation of the tumor suppressor PTEN leads to the rapid onset of aggressive malignant gliomas." (PMID 30279357, 2018). "HB-EGF mRNA expression is two- to five-fold higher in human glioblastomas than in normal brain tissue, and the HB-EGF receptors—EGFR homodimer and EGFR/ErbB2 heterodimer—are both commonly amplified in glioblastomas." (PMID 29864158, 2018). "In monolayer culture, uPAR functions in glioblastoma cell survival mainly after EGFR signaling is neutralized." (PMID 29445239, 2018). "Shikonin and its derivatives suppress the epidermal growth factor receptor signaling and synergistically kill glioblastoma cells in combination with erlotinib, possibly being a potential strategy to overcome drug resistance to erlotinib." (PMID 30459615, 2018). "Glioblastomas depend strongly on lipogenesis for rapid growth when they express the amplified tyrosine kinase receptor called epidermal growth factor receptor (EGFR) or its constitutively active mutant form EGFRvIII." (PMID 29784041, 2018). "The enforced expression of NFKBIA in both glioblastomas showing low NFKBIA expression or in those overexpressing EGFR, but with normal NFKBIA, resulted in inhibition of tumor growth." (PMID 30279357, 2018). "The analysis of glioblastomas bearing both EGFR and PDGFRA amplifications provided evidence for a consistent degree of heterogeneity at the level of the cell populations of a single tumor." (PMID 30279357, 2018). "EGFRvIII is an autophosphorylated-form of EGFR and presents in half of glioblastomas with EGFR amplification." (PMID 30373180, 2018). "EGFR amplification does not preclude an unusually long survival, as 26% of glioblastoma patients surviving longer than 3 years have glioblastoma with EGFR amplification as in the L group of this study." (PMID 29844869, 2018). "EGFR mutations in NSCLC and glioblastomas, treated with erlotinib hydrochloride, afatinib dimaleate, or lapatinib ditosylate." (PMID 29507702, 2018). "EGFR variant III (EGFRvIII), which is a truncated yet constitutively active form of EGFR, is present in 20–30% of glioblastoma tumors." (PMID 29615902, 2018).